CRP (C-reactive protein)
Diseases named in the same sentence as CRP in open-access papers (continued):
Sharing a sentence is not in itself a finding about the gene and the disease.
metabolic syndrome (continued). "A meta-analysis assessing the effect of different diets on markers of inflammation in patients with metabolic syndrome described a positive effect of low-fat diets on the reduction in CRP." (PMID 36364839, 2022). "The keywords of “impaired glucose tolerance, metabolic syndrome, improves glycemic control, C-reactive protein, and colorectal cancer” had been studied extensively since 2011 or earlier." (PMID 35463021, 2022). "In a previous study, waist circumference was shown to be the variable related to metabolic syndrome with the strongest correlation with CRP." (PMID 35745249, 2022). "This was also true amongst urban Portuguese adults, as well as in an adult population-based study in Germany, where CRP levels were significantly higher in individuals having elevated FBG levels, and were associated with metabolic syndrome occurrence." (PMID 34991564, 2022). "A study conducted in a sample of Japanese men and women during their hospital visits for health screening tests showed a stable and strong correlation between CRP level and metabolic syndrome (MetS), more importantly in women." (PMID 36289836, 2022). "Under specific environmental conditions (high fructose/sucrose or folate deficient diets) or after genetic modification (e.g., when expressing resistin or CRP transgenes), SHR animals also develop disturbances associated with metabolic syndrome." (PMID 35203486, 2022). "In this study, as the UHR quartiles increased, the prevalence of impaired fasting glucose and metabolic syndrome gradually increased, and the inflammatory index and C-reactive protein tended to increase." (PMID 35740443, 2022). "Our previous studies show that the combination of both diseases increases CRP, calprotectin and angiopoietin-like 8 levels, DNA damage, and chromosomal aberrations compared to patients with either psoriasis or a metabolic syndrome alone." (PMID 36556186, 2022). "Compared to controls, patients with PsA had a higher CVRFs (BMI, prevalence of HT, triglycerides, CRP, prevalence of smoking, and prevalence of metabolic syndrome)." (PMID 35665348, 2022). "The inflammatory status of the women was measured using the hs-CRP test, this is a validated low-grade chronic inflammatory marker that is related to dyslipidemia and cardiovascular disease." (PMID 35719139, 2022). "Other classical risk factors for the increased risk of CVD in individuals with high BMI are systemic inflammation (CRP), dyslipidemia and glucose intolerance." (PMID 35783839, 2022). "The keywords of “impaired glucose tolerance, metabolic syndrome, improves glycemic control, C-reactive protein, colorectal cancer” had been studied extensively since 2011 or earlier." (PMID 35463021, 2022). "HIV infection, CRP levels and metabolic syndrome were reported as predictors of CIMT in a few studies." (PMID 35819948, 2022). "After ~8-11 months of WD feeding, dams were similar in body weight but exhibited mild, systemic inflammation (elevated CRP and neutrophil count) and dyslipidemia (increased triglycerides and cholesterol) compared with dams fed a control diet." (PMID 36935840, 2022). "Patients with metabolic syndrome have elevated serum levels of proinflammatory mediators such as tumor necrosis factor-alpha interleukin-6 and C-reactive protein." (PMID 36361416, 2022). "As a result, CRP increases during certain inflammatory conditions, such as rheumatoid arthritis, metabolic syndrome, and cardiovascular disease." (PMID 35757631, 2022). "It has also been shown that in combination with antioxidants, RYR reduces high sensitivity to C-reactive protein (hs-CRP) and endothelial dysfunction, as well as effectiveness in dyslipidemia." (PMID 34357969, 2021). "Metabolic syndrome and its components except DBP were positively associated with WBC and metabolic syndrome, BMI, waist circumferences, and serum HDL and AST concentrations were positively related to serum CRP concentrations." (PMID 34371818, 2021).
metabolic syndrome (continued). "We reported recently that IL‐38 plasma concentrations correlate inversely with IL‐6 and CRP in overweight subjects, and are most reduced in subjects with metabolic syndrome." (PMID 33620105, 2021). "On the other hand, using Léger's and LM-LBM formulae, hyperfiltrating subjects of both sexes presented a higher prevalence of general and central obesity, dyslipidemia, fasting hyperinsulinemia, and CRP > 3 mg/L compared with their hypofiltrating peers." (PMID 34778125, 2021). "In children suffering from PH, the activation of the innate immune system is closely associated with the presence of metabolic syndrome, and high sensitivity C-reactive protein (hsCRP) levels correlate with a number of metabolic syndrome criteria." (PMID 32388582, 2021). "A relationship between metabolic syndrome and high CRP was also found in a Chilean study, but it was confirmed only in men." (PMID 34440486, 2021). "The high serum concentrations of CRP in adultindividuals with metabolic syndrome are a strong relationship between theaccumulation of visceral fat and increased LDL levels." (PMID 34755765, 2021). "TNF-α inhibitors also significantly reduce CRP levels in patients who have either metabolic syndrome or Crohn’s disease." (PMID 34829740, 2021). "OPG level positively correlates with CRP in adult patients with metabolic syndrome, and TNFα together with IL-1β stimulated production of OPG by human retinal microvascular endothelial cells." (PMID 33604725, 2021). "There is a consensus that inflammatory pathways play a critical role in progression and development of the metabolic syndrome with elevated acute-phase proteins such as C-reactive protein (CRP) and cytokines." (PMID 34327018, 2021). "Human trials of hesperidin in people with metabolic syndrome or type-2 diabetes reported reductions in inflammatory markers, including CRP." (PMID 34249019, 2021). "Increases in the concentration of either TNF-α or CRP have also been reported alongside dyslipidemia and obesity." (PMID 33731756, 2021). "The least square means of serum S14 level were estimated after adjustment for potential confounding factors (age, sex, BMI, HOMA-IR, CRP, metabolic syndrome, exercise time, menopause, smoking behavior) with different visceral fat level stratification." (PMID 34921174, 2021). "The first study found adherence to a DASH diet and lower levels of CRP, in a female cohort of patients with metabolic syndrome." (PMID 33503979, 2021). "C-reactive protein is a plasmatic protein used as a biomarker for the diagnosis of a series of health problems such as ulcerative colitis, cardiovascular diseases, metabolic syndrome, due to its essential role in the evolution of chronic inflammation." (PMID 34155310, 2021). "CRP has been shown to be an independent predictor of future cardiovascular events in metabolic syndrome patients." (PMID 34327018, 2021). "Unsurprisingly, several metabolic syndrome components (waist circumference and triglycerides), alongside chronic systemic inflammation (CRP) were higher in those with sarcopenic obesity." (PMID 33853546, 2021). "Wildman criteria also included HOMA-IR, the core concept of metabolic syndrome, and CRP, the best biomarker of vascular inflammation and predictor of CVD events." (PMID 32257643, 2020). "In this context, lipoprotein(a) [Lp(a)] and high sensitivity C-reactive protein (hs-CRP) are of interest given their associations with CVD risk and their roles in pro-inflammatory atherogenic dyslipidemia and general inflammation, respectively." (PMID 33299770, 2020). "Inflammation markers (IL-6, TNF-a and CRP) correlate positively with weight, and the metabolic syndrome is related to pro-inflammation and coagulation." (PMID 33108241, 2020). "Concerning the high prevalence of metabolic syndrome, as well as the high availability and easy interpretation of hs-CRP, this finding has practical clinical application." (PMID 32823680, 2020).
metabolic syndrome (continued). "It has been reported that PD is significantly associated with upregulation of biomarkers responsible for endothelial dysfunction and dyslipidemia such as CRP, tissue plasminogen activator (t-PA), and LDL-cholesterol (C), TNF-α." (PMID 33521070, 2020). "Metabolic syndrome, lipid profile and high-sensitivity c-reactive protein in participants with low, normal, and high body mass index." (PMID 32226033, 2020). "Previous studies have reported that elevated GGT and CRP levels increased the risks of dyslipidemia, metabolic syndrome, and CVD, yet their prognostic values of CVD events in T2D patients remain controversial." (PMID 33374401, 2020). "Several factors or diseases affect aortic stiffness, including increasing age, smoking, obesity, hypertension, dyslipidemia, impaired glucose tolerance, diabetes mellitus, metabolic syndrome, hyperhomocysteinemia, and high C-reactive protein levels." (PMID 32527291, 2020). "The markers of inflammation (CRP), metabolic syndrome (HbA1C) and gut permeability (zonulin) normalized." (PMID 32197409, 2020). "Inflammation markers (IL-6, TNF-a and CRP) correlate positively with weight, and metabolic syndrome is related to pro-inflammation and coagulation." (PMID 33108241, 2020). "After further adjustments for metabolic syndrome components, fasting insulin, and hs-CRP were made, the differences in the IMT-mean of the cystatin C levels became borderline significant and remained significant across albuminuria categories." (PMID 33129312, 2020). "Consumption of a Mediterranean diet resulted in significantly lower IL-6 and CRP concentrations individuals with metabolic syndrome when compared to controls." (PMID 32878326, 2020). "Another study assessed CRP levels in participants with metabolic syndrome where 82 participants received amoxicillin and metronidazole while 83 participants received placebo." (PMID 32756461, 2020). "BMI and metabolic syndrome have been also associated with oxidative stress (MDA, MPO, CAT) and pro-inflammatory markers (IL-6, high sensitivity C-reactive protein)." (PMID 32824349, 2020). "As part of the adaptive reaction to infection from the immune system, inflammation measured by levels of serum inflammatory markers, such as interleukin 6 (IL-6) and C-reactive protein (CRP), can trigger a set of metabolic syndromes and behavioral regulations." (PMID 32140686, 2020). "Polymorphisms in the C-reactive protein (CRP) genes might have crucial role in the development of metabolic syndrome (MetS)." (PMID 32879918, 2020). "Low self-reported physical function was reported associated with the development of CKD, because of the probable connection between physical inactivity and the greater prevalence of metabolic syndrome and elevated CRP." (PMID 31580172, 2019). "On the other hand, increased BMI correlates with thickened IMT, whereas presence of dyslipidemia and elevation of CRP correlate with plaque number." (PMID 31369578, 2019). "This is in line with previous surveys, which reported that serum CRP levels were frequently high in men with ED in the obese or metabolic syndrome population." (PMID 30976039, 2019). "The biologic profile showed a dyslipidemia (elevated total cholesterol and LDLc), high median erythrocyte sedimentation rate and C reactive protein." (PMID 31517250, 2019). "There was a U-shaped relationship of sleep duration with the components of metabolic syndrome and CRP." (PMID 31404954, 2019). "Metabolic syndrome and its associations with ALT, SUA, LDL and CRP in Beijing children were depicted in the present study." (PMID 31752150, 2019). "After CPAP treatment of about three months, patients showed a statistically significant decrease in ALT and markers of metabolic syndrome (leptin, CRP, and alpha-tocopherol/total lipid ratio)." (PMID 31540048, 2019).
metabolic syndrome (continued). "Information was missing on sex, age, physical activity, smoking, metabolic syndrome, BMI, hs‐CRP, and premature FH‐CHD for 2 (0.05%), 4 (0.1%), 291 (7.6%), 8 (2.0%), 15 (0.4%), 1 (0.03%), 5 (0.1%), and 107 (2.8%) participants, respectively." (PMID 31175686, 2019). "One meta-analysis reported that C18:3 administration had great therapeutic potential via decreasing patients’ inflammatory markers (e.g., C-reactive protein, IL-6, and TNF-α) that were associated with metabolic syndrome and related diseases." (PMID 31182969, 2019). "Systemic inflammation was measured by determining high sensitivity C-reactive protein (hsCRP) and dyslipidemia by lipid profile." (PMID 31060549, 2019). "IR was associated with a higher prevalence of dyslipidemia (low HDL-C, high TG), impaired fasting glucose, elevated hs-CRP, and hypoalbuminemia." (PMID 31309101, 2019). "Psoriasis patients with metabolic syndrome seem to have higher serum levels of IL-17, leptin, and c-reactive protein (CRP), while adiponectin levels seem to be lower." (PMID 32010143, 2019). "Of interest was the similarity in each group of waist circumferences, HDL-cholesterol (and in men fasting insulin and glucose) as metabolic syndrome (MetS) components, as well as of apoA-I, Lp(a), CRP, fibrinogen, and total testosterone levels." (PMID 30075607, 2018). "Age and proportion of females increased across tertiles of serum ADPN, while height, weight, BMI, WHR, CRP and the proportion of participants with metabolic syndrome decreased." (PMID 29609563, 2018). "The previous studies also revealed that the components of metabolic syndrome influenced the levels of CRP and NLR." (PMID 30454030, 2018). "The western dietary pattern, obese-related anthropometric parameters, and most components of metabolic syndrome are positively associated with CRP levels and NLR in men and women with metabolic syndrome." (PMID 30454030, 2018). "Components of metabolic syndrome were significantly increased with both CRP and neutrophil-to-lymphocyte ratio (NLR) levels." (PMID 30454030, 2018). "The indicators of central obesity such as waist or hip circumference and waist-to-hip ratio showed a strong positive correlation with CRP not only in healthy population, but also in the population with metabolic syndrome." (PMID 30454030, 2018). "After controlling for potential confounders, blood CRP, interleukin-6, and leptin were significant predictors of all five individual components of the metabolic syndrome (as both continuous and categorical outcome measures)." (PMID 30190688, 2018). "In middle-aged subjects with suspected metabolic syndrome, EAT was associated with inflammation represented by hs-CRP level, LV mass, and subclinical myocardial dysfunction only in men." (PMID 29960588, 2018). "Participants with metabolic syndrome were older and had lower adiponectin plasma levels, and higher HbA1c and high-sensitive C-reactive protein levels." (PMID 30151057, 2018). "Patients with dyslipidemia also had higher high-sensitivity C-reactive protein (Hs-CRP) levels (P < 0.001)." (PMID 30021605, 2018). "In a randomized, controlled dietary intervention for patients with the metabolic syndrome, bilberry supplementation reduced serum high-sensitivity C-reactive protein (CRP), IL-6, IL-12 and LPS levels, and downregulated genes associated with the TLR pathway." (PMID 30307962, 2018). "Not surprisingly, a great number of experimental and clinical studies have shown that metabolic syndrome is directly associated with circulating IL-6, TNF-α, and CRP, and that it is inversely correlated with IL-10 levels." (PMID 30558209, 2018). "Our main findings are that dietary patterns, anthropometric measurements, and metabolic parameters were directly associated with CRP and NLR among Taiwanese men and women aged 35 and above with metabolic syndrome." (PMID 30454030, 2018).
metabolic syndrome (continued). "The shared pathophysiology of GH and PE has been indicated by dyslipidemia (suggesting the ongoing atherosclerotic processes) in early gestation and elevated C-reactive protein (implicating inflammation) in previous studies." (PMID 28437461, 2017). "Each component of the metabolic syndrome increases risks for PE especially when C-reactive protein is elevated." (PMID 28451583, 2017). "Among the NASH group the 72 patients (86%) were males; the mean age was 41 ± 13, the mean body mass index was 25.3 ± 4.7, patients who meet the criteria of metabolic syndrome were 88 patients (72%), and the mean C-reactive protein level was 1.1 ± 0.7." (PMID 28127545, 2017). "T2DM patients had higher Hs-CRP with significant difference (P = 0.006) and higher dyslipidemia, Scr and history of stroke at the very edge of significance compared to non-T2DM patients." (PMID 28893252, 2017). "In this study, we examined the synergistic effect of CRP and metabolic syndrome on intraocular pressure." (PMID 28885336, 2017). "It was found that the level of CRP increases with the increasing number of signs of metabolic syndrome (MetS)." (PMID 29068430, 2017). "The highest intraocular pressure was observed in subjects with metabolic syndrome in the highest CRP tertile (P value for trend < .001)." (PMID 28885336, 2017). "Herein, we correlated serum tartrate-resistant phosphatase isoform 5a levels with metabolic syndrome status and made comparisons with traditional markers of inflammation, including c-reactive protein and interleukin-6." (PMID 29100456, 2017). "Under the conditions of a fructose-induced metabolic syndrome, high serum UA and CRP correlate to the development of early renal disorders without a clinical manifestation of renal dysfunction." (PMID 29321950, 2017). "The pathogenesis of atherosclerosis is connected to dyslipidemia and markers of inflammation (e.g., CRP and IL-6), as well as other cytokines and adhesion molecules which affect endothelial cell activation." (PMID 27527149, 2016). "CRP levels in blood are used to measure inflammation, but is also elevated in liver of obese humans, independently if they suffer from metabolic syndrome and NASH." (PMID 27902747, 2016). "Multivariable linear regression estimating associations between pericardial fat and right ventricular structure and function after accounting for metabolic syndrome, markers of systemic inflammation (CRP & IL-6), and in left ventricular morphology (n = 3,988)." (PMID 27311062, 2016). "There is controversy as to whether CRP actively contributes to disease progression andconsidered as a true risk factor for certain chronic diseases, or is simply a biomarker of the chronic inflammatory state that accompanies conditions such as dyslipidemia and atherosclerosis." (PMID 27633999, 2016). "Particularly it has been shown a highly significant correlation between visceral adiposity and CRP, and also patients with increasing number of metabolic syndrome components presented a linear increase in CRP levels." (PMID 27029038, 2016). "The aim of this study was to investigate the association of plasma IgG levels against Aggregatibacter actinomycetemcomitans, Porphyromonas gingivalis, and Prevotella intermedia, C-reactive protein, and periodontal status with metabolic syndrome." (PMID 26871443, 2016). "An early MR study in a sample of 3218 women used haplotypes in the CRP gene as instruments to investigate the role of CRP in the metabolic syndrome." (PMID 26809778, 2016). "Two recent studies proved that FSH was a biomarker to assess the probability of metabolic syndrome better than C-reactive protein, leptin or SHBG in postmenopausal women." (PMID 25959422, 2016). "The severity of inflammation in the metabolic syndrome measured by determining C-reactive protein and leukocytes is influenced by the number of criteria that make up metabolic syndrome." (PMID 27275343, 2016).